SMAD4 (SMAD family member 4)
Diseases named in the same sentence as SMAD4 in open-access papers (continued):
Sharing a sentence is not in itself a finding about the gene and the disease.
meningioma (5 papers, 2012 to 2024). A generally slow growing tumor attached to the dura mater. "Variants typical for angiomatous (brain) meningioma are PIK3CA, KIT, PTPN11, CDH1, SMAD4, and SMARCB1; the variants typical for psammomatous meningioma are APC, FGFR2, HNF1A, STK11, and JAK3." (PMID 38476782, 2024). "The NF2/PIK3CD2B/ SMAD4 mutant IVM featured 1p LOH, which was previously linked to meningioma recurrence." (PMID 35049691, 2022). "Taken together, we were able to validate three new direct targets for miR-34a-3p, SMAD4, FRAT1 and BCL2, which are likely to be implicated in the deregulation of signaling pathways that are already known to be involved in meningioma genesis and progression." (PMID 28340489, 2017). "In meningioma cells, overexpression of miR-34a-3p resulted in decreased protein levels of SMAD4, FRAT1 and BCL2, while inhibition of miR-34a-3p led to increased levels of these proteins as confirmed by Western blotting." (PMID 28340489, 2017). "Our findings support the idea that increased miR-34a-3p levels may contribute to a decreased cellular proliferation of meningioma cells in vitro via reduced SMAD4 and FRAT1 levels." (PMID 28340489, 2017). "After extracting and overlapping the downregulated genes during every stage of meningioma development within three datasets, we identified 497 genes, including well-defined tumor suppressor genes PTEN, PML, EP300, and SMAD4." (PMID 37791390, 2024). "We show that SMAD4, FRAT1 and BCL2 are direct targets of miR-34a-3p and that deregulation of miR-34a-3p alters proliferation and apoptosis of meningioma cells in vitro." (PMID 28340489, 2017). "Although loss of chromosome 18q occurs in higher-grade meningiomas, alterations of the SMAD4 gene locus apparently do not play a role in the pathogenesis of meningiomas." (PMID 28340489, 2017). "TGFβ signaling pathway was also found activated in fibroblastic meningioma, since multiple key genes in the pathway were up-regulated in tumor tissues by qRT-PCR, including TGFB2 (4.95-fold), TGFBR1 (2.43-fold), SMAD2 (2.82-fold), and SMAD4 (3.24-fold)." (PMID 23285163, 2012). "The hypothesized effects of downregulation of SMAD4 and FRAT1 on proliferation and upregulation of BCL2 on apoptosis of meningioma cells and the link to deregulation of miR-34a-3p should be explored further, also in malignant meningioma cell lines." (PMID 28340489, 2017).
metastatic colorectal cancer (5 papers, 2018 to 2022). "The strength of our study is the comprehensive evaluation of the four most highly mutated genes, to stratify prognosis in patients with metastatic colorectal cancer harboring SMAD4 mutation." (PMID 35892903, 2022). "In this study, the impact of coexisting mutations with SMAD4 on overall survival was evaluated retrospectively in 433 patients with metastatic colorectal cancer." (PMID 35892903, 2022). "Prior studies have resulted in conflicting conclusions on the value of SMAD4 mutations as a prognostic biomarker in metastatic colorectal cancer." (PMID 35892903, 2022). "Similar results revealed that mutations in BRAF and SMAD4 were significantly correlated with the overall survival (BRAF: p = 4.47 × 10−6 and SMAD4: p = 0.048) of patients with metastatic colorectal cancer." (PMID 36142267, 2022). "Recently, SMAD4 and NF1 mutations were reported as potential biomarkers for poor prognosis to cetuximab-based therapy in metastatic colorectal cancer patients." (PMID 34205170, 2021). "We hypothesized that the co-occurrence of frequently mutated oncogenes with SMAD4 would be more valuable as a prognostic biomarker than SMAD4 alone in patients with metastatic colorectal cancer." (PMID 35892903, 2022). "In patients with metastatic colorectal cancer, some studies have correlated SMAD4 mutation with worse overall survival, while others could not confirm such a finding." (PMID 35892903, 2022).
neuroblastoma (5 papers, 2016 to 2024). Neuroblastoma (NB) is the most common solid, extracranial childhood tumor. "This interaction leads to reduced transactivation of SMAD4, thereby promoting the stem cell activity of neuroblastoma (NB) cells." (PMID 39430249, 2024). "The Smad4 immunoreactivity was significantly lower in NB cases with poor differentiation (P < 0.001), higher mitosis karyorrhexis index (MKI) (P = 0.002), and advanced international neuroblastoma staging system (INSS) stages (P = 0.016)." (PMID 27595937, 2016).
oral cancer (5 papers, 2014 to 2025). "SMAD4 has been reported to be frequently mutated in multiple oral cancer cell lines such as CAL-27, CAL-33, and UM-SCC-2, and is a driving factor for altering the antiproliferative function of TGF-β signaling in many cancers." (PMID 40338154, 2025). "Notably, in SMAD4-deficient CAL-27 oral cancer cells, only GIPC1 is essential for TGFBR3-induced suppressive activity." (PMID 32471132, 2020). "In SMAD4-positive OC-2 oral cancer cells, both ARRB2 and GIPC1 participate in TGFBR3-mediated inhibition of migration and invasion." (PMID 32471132, 2020). "In SMAD4-positive OC-2 oral cancer cells, TGFBR3-mediated suppression requires both of its cytoplasmic interacting partners ARRB2 and GIPC1." (PMID 32471132, 2020). "In summary, our data show that SIRT1 inhibited the EMT process in oral cancer by deacetylating Smad4 and repressing expression of MMP7." (PMID 25424420, 2014). "Our findings suggest the SIRT1/Smad4/MMP7 pathway as a target for oral cancer driven by EMT." (PMID 25424420, 2014). "These experiments showed that Smad4 regulates and is required for MMP7 expression, secretion, and activity in oral cancer." (PMID 25424420, 2014). "We next investigated whether ARRB2 or GIPC1 plays a role in SMAD4-independent, TGFBR3-mediated migration and invasion of oral cancer cells by knocking down ARRB2 or GIPC1 in TGFBR3-overexpressing CAL-27 cells." (PMID 32471132, 2020). "Thus, SIRT1 participates in regulation of MMP7 activity and expression by deacetylating K37 of Smad4, and repressing the effect of TGF-β signaling in oral cancer." (PMID 25424420, 2014).
pancreatitis (5 papers, 2015 to 2025). Inflammation of the pancreas. "Both we and others have found SMAD4 and YAP1 nuclei staining in ADM of human pancreatitis tissue." (PMID 38247878, 2024).
prostate adenocarcinoma (5 papers, 2015 to 2024). "Progression to prostatic adenocarcinoma and distal metastases requires additional losses in tumor suppressors such as Rb or Smad4, mimicking their frequent losses in primary PC." (PMID 37292818, 2023). "In conclusion, this study has revealed a novel relationship between ETV1 and TGF-β/SMAD4, which may explain why ETV1 overexpression on its own is insufficient to cause the development of prostate adenocarcinomas." (PMID 31160676, 2019).
Ureteral obstruction (5 papers, 2018 to 2024). Obstruction of the flow of urine through the ureter. "In the kidney disease studies, Smad4 deficiency in a unilateral ureteral obstruction (UUO) model likely enhances both renal inflammation and fibrotic response." (PMID 36293110, 2022).
acinar cell carcinoma (4 papers, 2014 to 2021).
ampullary carcinoma (4 papers, 2012 to 2024). "This tumor also demonstrated a somatic nonsynonymous mutation in SMAD4 (mothers against decapentaplegic homolog 4), which has been observed previously in 50% of ampullary cancers but infrequently in bile duct cancers." (PMID 22762308, 2012).
asthma (4 papers, 2019 to 2024). "Other studies presented the role of miR-204-5p in interfering with TGFβ signaling pathways through regulating Six1 and SMAD4 genes in airway smooth muscle cells of asthma and human posterior capsule opacification, respectively." (PMID 38632250, 2024). "Our studies pointed out SMAD4 as a critical transcriptional factor involved in regulatory aspects of asthma pathogenesis." (PMID 32770056, 2020). "The study points out the possible role of 3′,5′-cyclic adenosine monophosphate (cAMP) signaling pathways via SMAD4 as a critical regulator in asthma inflammation." (PMID 32770056, 2020). "Additionally, the use of the DEK-targeting aptamer DTA-64 has been shown to reduce OVA-induced airway remodeling in asthma through the modulation of various signaling pathways such as Smad2/3, Smad4, p38MAPK, ERK1/2, JNK, and PI3K/AKT/mTOR." (PMID 38274803, 2023). "TGF-β-SMAD4 axis may be, therefore, explored as a novel therapeutic target to increase bronchodilators (mainly β2-adrenoceptor agonists) sensitivity in severe asthma." (PMID 32770056, 2020). "Here based on the study it can be hypothesized that in asthma repression of miR 34b/449 regulates upregulation of SERPINB2 mediated via SMAD4 upregulation by an unknown direct or indirect regulatory process." (PMID 32770056, 2020). "Based on our analysis, we identified mir-34b-5p and miR-449c-5p (members of the miR-34/449 family) as highest-ranked microRNAs involved in the regulation of FFL involving transcription factor SMAD4 and SERPINB2 hub gene in asthma." (PMID 32770056, 2020).
atherosclerosis (4 papers, 2020 to 2024). A disease characterized by the build-up of fatty material and calcium deposition in the arterial wall resulting in partial or complete occlusion of the arterial lumen. "All this evidence prompted us to speculate that Smad4 could play a role as a potential biomarker for atherosclerosis risk in OSA patients." (PMID 37175608, 2023). "Overall, this study highlights the potential role of sSMAD4 as a biomarker for early atherosclerosis risk in OSA patients and opens the path for new research on the potential role of SMAD4 as a relevant player in cardiovascular disease." (PMID 37175608, 2023). "Conversely, other studies suggest that Smad4 could exert a protective role, since its inhibition enhanced inflammation, reversed cholesterol transport, and promoted atherosclerosis by coordinating regulation of several genes related to the pathogenesis of this disorder." (PMID 37175608, 2023). "Interestingly, elevated soluble SMAD4 (sSMAD4) protein has been found in the plasma of OSA patients, the levels of which were even higher in those subjects with cardiometabolic comorbidities such as dyslipidemia or hypertension, two major risk factors for the development of atherosclerosis." (PMID 37175608, 2023). "Low-dose LPS and high-fat diet, led to an increased pro-inflammatory situation and aggravated atherosclerosis.Proinflammatory macrophages reduce IRAK-M by degradation of SMAD-4 that results in the generation of non-resolving inflammatory monocytes." (PMID 38396989, 2024). "Therefore, in this study, we analyzed the expression of Smad4 in OSA patients with or without early subclinical atherosclerosis and assessed potential mechanisms driving its overexpression and release to the plasma." (PMID 37175608, 2023). "Here, we analyzed soluble and intracellular SMAD4 levels in plasma and monocytes from OSA patients and non-apneic subjects, with or without early subclinical atherosclerosis (eSA)." (PMID 37175608, 2023).
Autoimmunity (4 papers, 2015 to 2024). The occurrence of an immune reaction against the organism's own cells or tissues. "SMAD4 has a critical role in T-cell function and is required in T-cell-mediated autoimmunity and tumour rejection." (PMID 35211795, 2022). "In order to rule out any potential extrinsic effects of the inflammatory environment (IBD or autoimmunity) and focus precisely on the specific intrinsic role of SMAD4 in CD8+ T cells, we opted to use naive F5 TCR–transgenic CD8+ T cells, which recognize a peptide from the influenza virus." (PMID 35426367, 2022). "Therefore, additional deletion of SMAD4 in TGF-βR–KO T cells prevents autoimmunity." (PMID 35426367, 2022). "Indeed, a recent study has demonstrated that Smad4 contributes to T cells function during autoimmunity and anti-tumor immunity independent of TGF-βR signaling." (PMID 26583325, 2015).
developmental delay (4 papers, 2016 to 2024). "Another case report involved a balanced translocation causing loss of the entire SMAD4 gene in a JPS-HHT patient, with dysmorphic features, intellectual disability, developmental delay, and corpus callosum agenesis." (PMID 38066625, 2023).
heart failure (4 papers, 2018 to 2025). Inability of the heart to pump blood at an adequate rate to meet tissue metabolic requirements. "Our results showed the same result in that the downregulated gene SMAD4 in MI samples was implicated in heart failure and low CRP value." (PMID 33224271, 2020). "We examined whether Smad3 and Smad4 can change in this isoproterenol‐induced heart failure model." (PMID 37482908, 2023). "The probability of heart failure was significantly increased in patients with high expression of SOCS3 and NRXN1, while the expression of CDK6 and SMAD4 was significantly reduced in patients without heart failure." (PMID 33224271, 2020).
hyperglycaemia (4 papers, 2020 to 2024). "Mechanistically, hyperglycaemia causes Smad4 localization to mitochondria in podocytes, and Smad4 directly binds to PKM2 and reduces the formation of active tetrameric form to decrease glycolysis." (PMID 38910890, 2024). "Hyperglycemia, the physiological condition that is most likely to cause increases in global O-GlcNAc levels, raised SMAD4 levels." (PMID 33199824, 2020).
Hypertension (4 papers, 2019 to 2023). The presence of chronic increased pressure in the systemic arterial system. "Indeed, gain-of-function mutations in SMAD4 lead to a plethora of cardiovascular abnormalities such as congenital heart defects, restrictive cardiomyopathy, and systemic hypertension." (PMID 37175608, 2023). "Circulating Smad4 protein levels in plasma were higher in OSA patients with hypertension than in patients with normal blood pressure (625.6 ± 246.9 vs. 426.1 ± 225.0 pg/mL, p = 0.010)." (PMID 32722512, 2020).
Immunodeficiency (4 papers, 2015 to 2022). Failure of the immune system to protect the body adequately from infection, due to the absence or insufficiency of some component process or substance. "Immune deficiency and damage to the serous membranes (pericarditis and pleurisy) are found recurrently in our cohort and in the literature, which clearly highlights the role of SMAD4 in the immune system." (PMID 35907855, 2022). "Loss or deficiency of SMAD family member 4 (SMAD4) in T cells often causes immune diseases." (PMID 36290667, 2022). "Patients with SMAD4 mutations should be followed up for both JPS and HHT, and physicians should be made aware of protein loosing enteropathy and immunodeficiency in JPS." (PMID 25705527, 2015). "More studies need to be conducted to determine whether SMAD4-mediated chemo-sensitization is involved in the tumor microenvironment or immunodeficiency." (PMID 36127339, 2022). "After Hg exposure, the SMAD4 and HDAC1 were down-regulated and DUOX was up-regulated in our study; these results suggest that Hg exposure could weaken the immune response and ability, as well as induce immune diseases." (PMID 36290667, 2022).
intracranial hemorrhage (4 papers, 2012 to 2025). Bleeding within the SKULL, including hemorrhages in the brain and the three membranes of MENINGES. "Constitutive endothelial-specific loss of Smad4 is embryonic lethal, while constitutive brain endothelial-specific Smad4 disruption resulted in intracranial hemorrhage and postnatal lethality." (PMID 39899215, 2025). "TGFβ signalling in ECs has also been shown to be critical for close interaction with pericytes as endothelial specific loss of Smad4, a central mediator of TGFβ signalling, leads to a reduced association between pericytes and ECs resulting in intracranial haemorrhage." (PMID 22745736, 2012). "This is an important observation in light of recent work showing that the brain hemorrhage and BBB defects in a cerebrovascular-specific knockdown of Smad4 are accompanied by pericyte detachment." (PMID 23862012, 2013).
intraductal papillary mucinous neoplasm (4 papers, 2014 to 2026).
leiomyoma (4 papers, 2007 to 2024). A well-circumscribed benign smooth muscle neoplasm characterized by the presence of spindle cells with cigar-shaped nuclei, interlacing fascicles, and a whorled pattern. "We demonstrated that simvastatin reduces SMAD2 and SMAD4 expression in leiomyoma stem cells, whereas it increases the expression of the inhibitory SMAD7." (PMID 35118811, 2022). "Tissue from UL has been shown to overexpress receptor‐activated SMAD3, common SMAD4 and TGF‐βRs in leiomyoma, compared to the myometrium." (PMID 35118811, 2022). "The expression of SMAD3, SMAD4 and phosphorylated SMAD3, as well as TGF-βR type I and type II, were all higher in leiomyoma when compared with those in myometrium." (PMID 25295107, 2014). "They included several genes such as NR2F1, PNN, Smad4, Smad5, STAT5B, JUN, TGIF2, and ATF1 that were over-expressed while RUNX3, STAT1, STAT6, EGR3, GAS7, Smad1, and EDF1 were underexpressed in leiomyomas as compared to keloid/incisional scars." (PMID 17718906, 2007). "Additionally, gonadotropin‐releasing hormone analog (GnRHa) therapy decreases TGF‐βRs, SMAD3 and SMAD4 along with an increase in SMAD7 expression in both myometrium and leiomyoma tissues compared to untreated control." (PMID 35118811, 2022).